EPB41L5 (erythrocyte membrane protein band 4.1 like 5)
Diseases named in the same sentence as EPB41L5 in open-access papers:
EPB41L5 is named in the same sentence as 27 diseases in open-access papers, as found by Europe PMC text mining. Sharing a sentence is not in itself a finding about the gene and the disease. The quoted sentences say what the papers report.
glioblastoma (5 papers, 2020 to 2024). The most malignant astrocytic tumor (WHO grade IV). "Low circ-EPB41L5 expression was associated with a poor prognosis in glioblastoma patients, although overexpression suppressed glioma cell proliferation, clone formation, migration, and invasion abilities, whereas suppression had the opposite impact." (PMID 35883576, 2022). "In this study, we detected the expression profile of circRNAs in glioblastoma and identified a circular RNA, termed as circ-EPB41L5, derived from the EPB41L5 gene, which was significantly downregulated in glioblastoma tissues and cell lines and associated with the prognosis of glioblastoma patients." (PMID 31905344, 2020). "Subsequent experiments deduced that circ-EPB41L5 was significantly downregulated in glioblastoma tissues and associated with several clinical features, including age, number of lesions, necrosis change, recurrence, survival, and prognosis of glioblastoma patients." (PMID 31905344, 2020). "They confirmed that circ6834 inhibited glioblastoma progression via circ6834/miR-19a/EPB41L5/p-AKT regulatory axis." (PMID 38890620, 2024). "Circ-EPB41L5 expression levels were significantly decreased in glioblastoma tissues and cell lines relative to normal brain tissues and cell lines." (PMID 35883576, 2022). "The study demonstrates that circ-EPB41L5/miR-19a/EPB41L5/p-AKT regulatory axis plays a significant role in glioblastoma progression, providing a fresh insight into the mechanisms underlying glioblastoma." (PMID 35883576, 2022). "EPB41L5 has been confirmed to play an oncogenic role in glioblastoma, gastric cancer, and breast cancers." (PMID 34285192, 2021). "The data highlighted that circ-EPB41L5 functions as a tumor suppressor and provides solid evidence to understand glioblastoma tumorigenesis and identify the potential therapeutic molecular targets for the treatment of glioblastoma." (PMID 31905344, 2020). "Taken together, low expression of circ-EPB41L5 presented a poor prognosis, acting as a putative suppressor in glioblastoma." (PMID 31905344, 2020). "In conclusion, we identified a dysregulated circRNAs profile in glioblastoma and a novel target circRNA, circ-EPB41L5, that serves as a suppressor in glioblastoma." (PMID 31905344, 2020). "In order to assess the function of EPB41L5 in glioblastoma, we first downloaded Rembrandt and TCGA datasets of glioma samples." (PMID 31905344, 2020). "To evaluate the clinical significance of circ-EPB41L5, we detected its expression in 45 glioblastoma patients whose clinical characteristics were known." (PMID 31905344, 2020). "Low circ-EPB41L5 expression was correlated to the poor prognosis of glioblastoma patients, while the overexpression inhibited proliferation, clone formation, migration, and invasion abilities of glioma cells, and the suppression had counter effects." (PMID 31905344, 2020). "In vitro and in vivo experiments demonstrated that the underexpression of EPB41L5 induced tumorigenesis of glioblastoma." (PMID 31905344, 2020). "The expression of EPB41L5 in different subtypes of glioblastoma was significantly increased as compared to the normal samples." (PMID 31905344, 2020). "Then, the correlation between circ-EPB41L5 expression and clinical features and the survival time of 45 glioblastoma patients was detected." (PMID 31905344, 2020). "To evaluate the role of circ-EPB41L5 in glioblastoma, we detected its expression in several glioblastoma cell lines and found that circ-EPB41L5 is downregulated in glioblastoma cells, especially in U87 and U251, as compared to the normal human astrocytes (NHA)." (PMID 31905344, 2020). "However, the level of EPB41L5 in glioblastoma was markedly lower than in astrocytoma and oligodendroglioma." (PMID 31905344, 2020). "Finally, we demonstrated that circ-EPB41L5/miR-19a/EPB41L5 axis promotes the tumorigenesis of glioblastoma via activated RhoC and phosphorylated AKT." (PMID 31905344, 2020).
glioblastoma (continued). "Taken together, EPB41L5 is shown to act as a suppressor in the progression of glioblastoma." (PMID 31905344, 2020). "Thus, we analyzed the expression of EPB41L5 in TCGA and Rembrandt databases and found that it was upregulated in the glioma but downregulated in glioblastoma as compared to LGG." (PMID 31905344, 2020). "Functionally, the overexpression of circ-EPB41L5 inhibited the proliferation, migration, and invasion of glioma cells, which suggested that circ-EPB41L5 might play a suppressor role in the pathogenesis and development of glioblastoma." (PMID 31905344, 2020). "Moreover, EPB41L5 was downregulated in mesenchymal glioblastoma that exhibits poor prognosis." (PMID 31905344, 2020). "Interestingly, the downregulated genes were found to be involved in Rap1, PI3K-Akt, and cell adhesion molecules that are crucial for tumorigenesis, and these results supported our hypothesis that circ-EPB41L5 acts as a suppressor in glioblastoma." (PMID 31905344, 2020). "Circ-EPB41L5 and circ-PAK7 were significantly downregulated in glioblastoma tissues." (PMID 31905344, 2020).
breast carcinoma (4 papers, 2016 to 2021). "Recent studies confirmed that EPB41L5 is involved in the occurrence and development of squamous cell carcinoma, gastric cancer, and breast cancer." (PMID 34285192, 2021). "We have previously shown that silencing of EPB41L5 in other types of cancers, such as breast cancer and renal cancer, drastically improves their drug-resistance." (PMID 27871329, 2016). "We next sought to identify EMT transcriptional factors primarily responsible to induce EPB41L5 in breast cancer cells." (PMID 27617643, 2016). "Consistently, we have shown that ZEB1 is central in inducing EPB41L5 in breast cancer cells and renal cancer cells." (PMID 27871329, 2016). "We found that EPB41L5 is expressed at high levels in malignant breast cancer cells and binds to AMAP1." (PMID 27617643, 2016). "Consistently, database analysis suggested that the EMT-TFs that induce EPB41L5 in tongue SCC appear to be different from those of breast cancer and renal cancer." (PMID 27871329, 2016). "We previously showed that EPB41L5 is the key molecule that drives mesenchymal malignancies in significant populations of breast cancer patients and renal cancer patients." (PMID 27871329, 2016). "Moreover, similarly to that in breast cancer cells, Arf6 and EPB41L5 were found to accumulate at the invadopodia of LPA-stimulated 786-O cells." (PMID 26854204, 2016). "ARF6 and its effector AMAP1 are often overexpressed in different types of cancers, such as breast cancer and renal cancer, and in these cancers, AMAP1 binds to EPB41L5 to promote invasion, metastasis, and drug resistance." (PMID 27871329, 2016). "In breast cancer cells, ligand-activated receptor tyrosine kinases employ GEP100 to activate Arf6, which then recruits AMAP1; and AMAP1 then binds to the mesenchymal-specific protein EPB41L5, which promotes epithelial–mesenchymal transition and focal adhesion dynamics." (PMID 26854204, 2016).
glioma (4 papers, 2020 to 2022). A benign or malignant brain and spinal cord tumor that arises from glial cells (astrocytes, oligodendrocytes, ependymal cells). "Circ-EPB41L5 is significantly under-expressed in glioma tissues and cells, and is closely associated with poor prognosis of the patients; functionally, circ-EPB41L5 inhibits glioma cell growth, colony formation, migration and invasion." (PMID 35264067, 2022). "Circ-EPB41L5 inhibits the proliferation, migration, and invasion of glioma cells by sponging miR-19a-3p and regulating the host gene EPB41L5 expression, which reduces the progression of glioma by inhibiting RhoC and p-AKT." (PMID 33946718, 2021). "Cell migration and invasion assays showed that the overexpression of circ-EPB41L5 impaired the migration and invasion abilities of glioma cells, and the downregulation presented an opposite role." (PMID 31905344, 2020). "Kaplan–Meier survival analysis in Rembrandt and TCGA datasets showed that glioma patients with low expression of EPB41L5 had a poor prognosis." (PMID 31905344, 2020). "Taken together, circ-EPB41L5 affected the proliferation, migration, and invasion of glioma cells by regulating the miR-19a-EPB41L5, RhoC, and p-Akt signaling pathways." (PMID 31905344, 2020). "circ-EPB41L5 inhibited the proliferation, migration, and invasion of glioma cells by sponging miR-19a and regulating the expression of the host gene EPB41L5 that suppressed the progression of glioma by inhibiting RhoC and p-AKT." (PMID 31905344, 2020). "The expression of EPB41L5 was significantly elevated in glioma tissues as compared to normal samples." (PMID 31905344, 2020). "Consecutively, we found that the expression of EPB41l5 mRNA was significantly increased in circ-EPB41L5 overexpressed glioma cells." (PMID 31905344, 2020). "Furthermore, circ-EPB41L5, which is down-regulated in GBM, is a circRNA gene that can inactivate the miR-19a, thereby inhibits the phosphorylation of the Akt through the EPB41L5 overexpression, and subsequently can repress the invasion and metastasis of glioma cells to inhibit the GBM tumorigenesis." (PMID 35090496, 2022).
gastric cancer (2 papers, 2021 to 2023). A primary or metastatic malignant neoplasm involving the stomach. "In a previous study, we reported that the expression of EPB41L5 induced by TGF-β1 promotes the migration and invasion of gastric cancer cells via TGF-β signaling." (PMID 36596853, 2023).
hepatocellular carcinoma (2 papers, 2016 to 2020). A malignant tumor that arises from hepatocytes. "It has also been found that EPB41L5 suppresses the invasion and metastasis of hepatocellular carcinoma." (PMID 31905344, 2020).
brain cancer (1 paper, 2020). A primary or metastatic malignant neoplasm affecting the brain. "However, EPB41L5 and SERINC3 had a high rank based on mutational burden and CNVs, ELOVL6 was annotated as an oncogene in prostate cancer, and PPM1H has been proposed to be an oncogene, due to its relation to PPM1D (a well-studied oncogene in breast, ovarian, and brain cancers)." (PMID 32605588, 2020).
breast tumors (1 paper, 2016). "Consistently, The Cancer Genome Atlas RNASeq data set on human primary breast tumors (n=970) indicated that high levels of ZEB1 mRNA statistically correlate with high levels of EPB41L5 mRNA." (PMID 27617643, 2016). "By analyzing The Cancer Genome Atlas RNASeq data set on primary breast tumors, we then found that high expression (top 33%) of EPB41L5 mRNA statistically correlated with the poor overall survival of patients." (PMID 27617643, 2016). "Therefore, ZEB1 is likely to have a key role in induction of the EPB41L5 gene in significant populations of primary breast tumors." (PMID 27617643, 2016).
glomerular disease (1 paper, 2021). "By combination with a highly podocyte-selective and essential gene like Epb41l5, our model allowed for efficient gene deletion of Epb41l5 in the podocytes of adult mice, resulting in podocyte depletion and the rapid onset of glomerular disease." (PMID 34203913, 2021).
lymph node metastasis (1 paper, 2016). "Tongue SCC patients, having been subjected to the curative resection of primary sites, were classified into two groups based on the presence (positive) or the absence (negative) of lymph node metastasis; and EPB41L5 protein expression at the primary lesions were evaluated by the H-score." (PMID 27871329, 2016).
ovarian carcinoma (1 paper, 2020). A malignant neoplasm originating from the surface ovarian epithelium. "To clarify the carcinogenic effect of ESRP1 in ovarian cancer, we found that ESRP1 inhibited cancer cell migration and invasion by alternatively splicing cytoskeleton-associated proteins Rac1 and EPB41L5, and promoted colonization and colony formation." (PMID 32467669, 2020).
Retinal dysplasia (1 paper, 2022). Abnormal growth and differentiation, structure and appearance of the retina present from birth. "In vertebrate models, mutation or loss of zebrafish (Danio rerio) orthologs of apicobasal polarity proteins EPB41L5 (zebrafish moe), MPP5 (nok), and CRB2 (ome) cause retinal developmental and lamination abnormalities similar to Crb1-associated retinal dysplasia." (PMID 35675330, 2022).
tongue SCC (1 paper, 2016). "Immunohistochemical staining of clinical specimens of tongue SCC demonstrated that high expression levels of EPB41L5 statistically correlate with poor disease-free survival and poor overall survival rates of patients." (PMID 27871329, 2016). "Our results indicate that activation of the cancer mesenchymal program in tongue SCC, which leads to EPB41L5 expression, closely correlates with the poor prognosis of patients." (PMID 27871329, 2016). "Thus, we propose that immunohistochemical staining of EPB41L5 provides a biomarker predictive for the prognosis of tongue SCC." (PMID 27871329, 2016). "However, unlike these types of cancers, we were unable to obtain evidence supporting the idea that EPB41L5 is the key molecule that drives the invasion and chemoresistance of tongue SCC." (PMID 27871329, 2016). "We here examined whether tongue SCC also express the mesenchymal component of the ARF6-based pathway, namely EPB41L5, and whether its expression correlates with malignancy." (PMID 27871329, 2016).
cancer (12 papers, 2010 to 2023). A tumor composed of atypical neoplastic, often pleomorphic cells that invade other tissues. "EPB41L5 has been linked to metastasis and EMT in different cancers [NCBI]." (PMID 36834486, 2023). "Furthermore, although ZEB1 can be critical in the cell plasticity generating cancer stem cells, we have yet to study the relationship between EPB41L5 expression and the generation of cancer stem-like cells." (PMID 27617643, 2016). "Interestingly, we identified statistically significant co-expression of CRB3 with EPB41L4B and/or EPB41L5 in several microarray studies of cell line panels, across the entire cell line panel of the Cancer Cell Line Encyclopedia, as well as a study of 21 primary human mammary epithelial cell lines." (PMID 30440051, 2018). "Erythrocyte membrane protein band 4.1 like 5 (EPB41L5) is an essential protein for EMT progression and metastasis in various types of cancer." (PMID 36596853, 2023). "Many of these isoforms (including CD44, ENAH, p120-Catenin, EPB41L5) show direct correlation with both MET-EMT and metastasis, in multiple cancer types." (PMID 24124593, 2013). "The most recently discovered 4.1 family member, the product of the EPB41L5 gene (also called Limulus), regulates cell adhesion during development, but has not yet been investigated in the context of human cancer." (PMID 20860828, 2010).
tumor (5 papers, 2016 to 2023). "In experiments on mice, the researchers found that ZBTB7A inhibits expression of the EPB41L5 gene, which codes for a protein which promotes tumor growth and metastasis." (PMID 36596853, 2023). "ZBTB7A negatively regulates GBM tumor progression by directly binding to the promoter of EPB41L5, an important gene involved in cell mobility, and repressing its transcription." (PMID 36596853, 2023). "We demonstrated that ZBTB7A dramatically inhibits GBM tumor growth through transcriptional repression of EPB41L5." (PMID 36596853, 2023). "Conversely, the overexpression of circ-EPB41L5 decreased the tumor formation in nude mice brain and impaired tumorigenesis caused by EPB41L5 knockdown." (PMID 31905344, 2020). "The results showed that knockdown EPB41L5 led to a marked increase in tumor volume with short survival time." (PMID 31905344, 2020). "We further investigated the effects of circ-EPB41L5 and its host gene on regulating the tumor growth in vivo." (PMID 31905344, 2020). "The expression of EPB41L5 was significantly decreased in ZBTB7A-overexpressing tumor tissues." (PMID 36596853, 2023). "Overall, we discovered the role of a novel tumor suppressor that directly inhibits GBM progression (ZBTB7A) and identified EPB41L5 as a therapeutic target protein for patients with GBM." (PMID 36596853, 2023). "The protein expression of EPB41L5 and ZBTB7A was observed in mouse tumor tissues injected with control U343 cells and ZBTB7A-expressing U343 cells using IHC analysis." (PMID 36596853, 2023). "In this regard, circ-EPB41L5 (YMO1) is a direct target for miR-19a and is a critical tumor suppressive molecule that interacts with RhoC and inhibits its expression." (PMID 35090496, 2022). "After observation for 4 weeks, the GBM tumor volume was significantly increased in a mouse injected with shZBTB7A-expressing U87 cells compared to that in the control mice, and the protein expression levels of ZBTB7A and EPB41L5 in GBM tumor tissues were inversely correlated." (PMID 36596853, 2023). "ZBTB7A overexpression did not promote tumor growth in vivo in GBM models, but it suppressed the expression of EPB41L5, a target of ZBTB7A." (PMID 36596853, 2023).
kidney disease (1 paper, 2023). "Noteworthy candidates supported by kidney phenotypes in model organisms but not yet established as human kidney disease genes include EPB41L5 and FNIP1." (PMID 36890159, 2023).
EPB41L5 also shares sentences with these, for which no sentence is quoted: renal carcinoma (2 papers); squamous cell carcinoma (2); astrocytoma (1); colon cancer (1); liver cirrhosis (1); lung carcinoma (1); nephrotic syndrome (1); non-small cell lung carcinoma (1); oligodendroglioma (1); pancreatic cancer (1); prostate adenocarcinoma (1); prostate carcinoma (1).